RB1 (RB transcriptional corepressor 1)
Diseases named in the same sentence as RB1 in open-access papers (continued):
Sharing a sentence is not in itself a finding about the gene and the disease.
tumor (continued). "We previously reported a CAF case with monoallelic 13q14 deletion in which the tumor expressed decreased levels of FOXO1 and RB1, both of which were encoded in 13q14, and increased reactive oxygen species (ROS) levels." (PMID 28887603, 2018). "RB1 is a tumor suppressor that undergoes periodic phosphorylation when cells transverse the cell cycle." (PMID 29451912, 2018). "SJRB051 had a complex genome structure (due to chromothripsis) that included biallelic rearrangement of RB1 on chromosome 13 with an estimated tumor purity of 0.75 and 0.97 for the PCGP and clinical pilot sample, respectively." (PMID 30262806, 2018). "The observation is consistent with exome sequencing of 150 mCRPC tissues which revealed that biallelic inactivation always had occurred if a high-impact event was observed in a key tumor suppressor such as PTEN or RB1." (PMID 30458854, 2018). "In primary cultures of mouse embryonic fibroblast (MEFs) the loss of Rb1 promote RAS mutation, activating an axis for tumor initiation." (PMID 30065348, 2018). "The rb1Δ7/Δ7 mutant transcriptome and phenotypic analyses showed that rb1/rb1 mutant cells can re-enter the cell cycle and proceed into M phase, but lack continuous unregulated proliferation characteristic of rb1-transformed tumor cells." (PMID 29914980, 2018). "The canonical tumor suppressor role of RB1 is to regulate proliferation by transcriptional repression of E2F targets driving cell cycle entry." (PMID 29914980, 2018). "RBBP4, a chromatin adaptor for multiple chromatin remodeling complexes, is an E2F target and, as expected, was increased in the zebrafish rb1 tumor and rb1/rb1 homozygous mutant transcriptome." (PMID 29914980, 2018). "Of the 3302 transcriptional regulators in the zebrafish genome, 1191 were differentially expressed in the rb1 tumor transcriptome, and 122 were differentially expressed in the rb1/rb1 mutant transcriptome." (PMID 29914980, 2018). "Our findings showed that the up-regulated Linc00441 was inversely correlated with RB1 expression in human GC tumor samples." (PMID 30680063, 2018). "Deletions affecting RB1 are also frequent (approximately 26% of tumours) and also occur in both VP-MCCs and VN-MCCs78,80,81." (PMID 30287935, 2018). "Our study provides novel insights into the tumor suppressive role of zebrafish Rb1 and its candidate interacting proteins Rbbp4 and Hdac1 in driving persistent tumor growth, and identifies Rbbp4 as a potential target to inhibit tumor cell survival." (PMID 29914980, 2018). "These events reinforce the previous illustration in GBM that hypermethylation and deletion of RB1 and CDKN2B respectively contribute to the loss of tumor suppressor function." (PMID 30059495, 2018). "These cell lines were then evaluated for the effects of RB1 loss towards susceptibility to BET inhibition, in terms of effects on tumor cell viability as well as effects on immune phenotype." (PMID 30400835, 2018).
tumor (continued). "Other known tumour suppressors, such as RB1 and PTEN, can readily be inactivated by both homozygous deletions and inactivating point mutations (often in combination with loss-of-heterozygosity of the other allele)." (PMID 29089486, 2017). "The average age of tumor incidence was 7.5 months after birth, and 7 of 30 (23.3%) wild type zebrafish injected with rb1-TALEN mRNA at one-cell stage died bearing tumors in head regions." (PMID 28903419, 2017). "The retinoblastoma protein (RB1) is one of the most frequently affected tumor suppressors across multiple cancer histologies and plays a critical role in regulation of cell cycle and apoptosis." (PMID 28390395, 2017). "The same applies to RB1, which is up-regulated in 2 tumour types (CHOL and HNSC) but it is down-regulated in another 4 tumours (BLCA, LIHC, LUAD, LUSC), consistent with the effect on the whole pathway." (PMID 28387377, 2017). "QuantSeq 3′ mRNA sequencing was performed in order to characterize the molecular features of tumor tissues induced by rb1-TALEN injection." (PMID 28903419, 2017). "Among these genes, many are involved in tumour suppression [e.g. RB1], apoptosis [e.g. BCL2L1], the cell cycle [e.g. CCND1, CCND2] or protein kinases [e.g. KIT, GSK3‐β]." (PMID 28539478, 2017). "This tumor model expresses Cre recombinase from the CHX10 promoter to inactivate RB1 and p107 genes in the retina to deregulate E2F-dependent proliferation and apoptosis." (PMID 28445155, 2017). "Out of 16 analyzed TNBC tumors, six, three, two, and one tumor harbored SVs involving RB1, KMT2C, PTEN, or RUNX1, respectively." (PMID 28636652, 2017). "About 50% of the tumor cells of rb1-TALENs injected tp53e7/e7 mutant zebrafish displayed highly mitotic features." (PMID 28903419, 2017). "Cyclin-dependent kinase 2 (Cdk2) is a key cell cycle regulator, with roles in inactivating phosphorylation of the RB1 (pRb) tumour suppressor family and in controlling both G1/S and G2/M transitions." (PMID 29044141, 2017). "The human RB1 gene was the first gene isolated with tumor suppressor activity and it is expressed in a wide variety of tissues." (PMID 29261756, 2017). "Retinoblastoma 1 (RB1) protein is an important tumor suppressor which is involved in cancer cell related processes including cell cycle, cell differentiation and apoptosis." (PMID 29069869, 2017). "In two of the three tumors (rb1-TALEN-T2, rb1-TALEN-T3), all alleles showed frame-shift mutations; for the other tumor (rb1-TALEN-T1), 25% (9/36) of mutant alleles were in-frame mutations." (PMID 28903419, 2017). "We found a aberrant lower fluorescence of RB1 in the slice resected from the Linc00441 overexpressed Hep3B-induced tumor." (PMID 28300839, 2017). "PDK1 mRNA was significantly overexpressed in RB tumor samples as well as Y79 and Weri-Rb1 cells compared to normal retinal tissue." (PMID 28505181, 2017). "H & E staining was performed to analyze tumor tissues from rb1-TALEN mRNA injected tp53e7/e7 mutant zebrafish." (PMID 28903419, 2017).
tumor (continued). "Subcutaneous tumor formed by A549 transducing with LV-miR-661 showed less RB1 staining, suggesting that RB1 was a direct target of miR-661." (PMID 28716024, 2017). "RB1 often inhibits tumor cell proliferation by regulating genes required for G to S phase transition and causes G1 cell cycle arrest." (PMID 29069869, 2017). "Observations in various human cancers in which genetic inactivation of RB1 has been reported, and the analysis of genetically engineered mice have identified pRb as a major tumor suppressor." (PMID 27966456, 2017). "Wild-type RB1 mutation status, used as a surrogate marker of YAP1 expression, was prognostic for decreased patient survival and increased chemo-refractory tumor response." (PMID 29088741, 2017). "RBL1 is a tumor suppressor that has the same function as the retinoblastoma 1 (RB1) gene, which involves in cell cycle regulation." (PMID 27779109, 2017). "HPV E7 is well known to subvert E2F regulation by binding and enhancing the degradation of the RB1 tumor suppressor and the related RBL1 (p107) and RBL2 (p130) proteins as well as through other mechanisms." (PMID 28968467, 2017). "The final analysis confirmed RB1 mutation, TERT copy gain, histotype and tumour stage as independent factors for poor prognosis." (PMID 27873319, 2017). "The analysis of DMD genetic alterations revealed a high frequency of gene mutations, which was similar to other well-known tumor suppressor genes (BRCA1, BRCA2, PTEN, RB1)." (PMID 27391342, 2017). "In the course of developing tumor suppressor gene knockout progeny, we observed that somatic gene inactivation of cdkn2a/b and/or rb1 efficiently induced tumors in the F0 founder generation." (PMID 28903419, 2017). "Both ELF2A and ELF2B uniquely interact with the haemopoietic transcriptional co-regulator and proto-oncogene LMO2 whilst ELF1 specifically interacts with the tumour suppressor RB1." (PMID 28351373, 2017). "This due to the expected selective growth advantage of this hypothetical population of rb1 mutant tumor cells and the large original cohort size (n = 50)." (PMID 27739525, 2016). "This shows methylation in the 27 CpGs of the RB1 promoter, including binding CpGs to transcription factors but with varying methylation density both among the CpGs and from tumor to tumor." (PMID 26753011, 2016). "This is consistent with in vitro data that show that Brg1 is a required cofactor for Rb1-mediated growth inhibition in human tumor-derived cell lines." (PMID 28105458, 2016). "Apart from the three genes (RB1, BCOR, CREBBP) that showed somatic mutations in at least 2 different tumors, there were 199 other genes that were mutated in a single tumor only." (PMID 27126562, 2016). "Brg1-negative tumor cells primarily harbored hypophosphorylated Rb1 (pRb1Hypo), so none of the mechanisms of Rb1 inactivation (pRb1Hyper) accounts for how the Rb1 pathway is inactivated in Brg1-negative tumor cells." (PMID 28105458, 2016).
tumor (continued). "For these tumors, the homozygosity at the RB1 locus (mBAF values) is indicative for tumor cellularity." (PMID 27115612, 2016). "In the same experiment, we observed a transient downmodulation of hypo-Rb1, which represents inactivation of the tumor suppressive function of Rb1 downstream of the PDGFRα/PDGFAA axis." (PMID 27344175, 2016). "When considering the estimation of the percentage of tumor cells harboring the mutation, i.e., CCF, we found that ESR1 and RB1 mutations were mostly identified as subclonal (ESR1: 14/21 mutations [67%]; RB1: 5/10 mutations [50%])." (PMID 28027327, 2016). "RB-1 (a tumour suppressor gene, which regulates cell survival and cell death) was significantly (p < 0.001) increased by baicalein treatment at both concentrations." (PMID 27586635, 2016). "This indicates that in WT tumor cells, when Rb1 is hypophosphorylated, tumor cells grow more slowly." (PMID 28105458, 2016). "The pocket protein (PP) family consists of the three members RB1, p107 and p130 all possessing tumor suppressive properties." (PMID 27121059, 2016). "Remarkably, our study showed that copy number gains rarely exceeded change of one copy, even in pure tumor samples with 100% homozygosity at the RB1 locus (N = 34), which is indicative for intra-tumor heterogeneity." (PMID 27115612, 2016). "We have previously reported that combined Rb1-Rbl1 or Rb1-E2f1 ablation in epidermis produces important alterations in epidermal proliferation and differentiation, leading to tumor development." (PMID 27708231, 2016). "We then examined the phosphorylation status of Rb1 in Brg1-positive tumor cells using dual IF with antibodies against Brg1 and pRb1S780 in tumors from each of the four genotypes." (PMID 28105458, 2016). "For the tumor suppressors RB1, NF1, and SMAD4, the high-amplitude deletions (<−0.9) are not cleanly separated from the other bins by expression." (PMID 26787600, 2016). "Taken together, our results provide evidence of an Rb1-dependent Ets1-Zeb1 amplification loop in thymocyte differentiation and tumor invasion." (PMID 25880398, 2015). "Rb1 has been reported to function as a tumor suppressor and to play critical roles in controlling the rate of cellular growth and of tumorigenesis." (PMID 26467212, 2015). "The future success of trials evaluating CDK4/6 inhibitors in CRPC is likely to hinge on enrichment with patients whose tumours exhibit cyclin/CDK activation in the background of intact RB1." (PMID 25896606, 2015). "Here, we confirmed that Rb1, an important tumor suppression gene (TSG), is a direct target of miR-155 which is directly up-regulated by MCRS1." (PMID 26467212, 2015). "Whereas RB1 is a well-established tumor suppressor gene at 13q14, the tumor suppressor function of KLF5 has also been demonstrated in both xenograft and knockout models." (PMID 25896712, 2015). "Rb1 and P16 show inverse expression pattern according to tumor grade with more frequent Rb1 in low grade vs. more frequent P16 in grade 3 tumors." (PMID 26043844, 2015). "Since its discovery as the first tumor suppressor gene almost 30 years ago, RB1 has represented an appealing target for cancer therapy." (PMID 26160835, 2015). "In this study we deleted Rb1 and Pten from osteoprogenitor cells to determine the consequences for bone development and tumor formation." (PMID 26317218, 2015).
tumor (continued). "We confirm a number of previously published molecular changes associated with high risk disease, including MYC amplification, and NKX3-1, RB1 and PTEN deletions, as well as over-expression of PCA3 and AMACR, and loss of MSMB in tumour tissue." (PMID 26501111, 2015). "Conversely, the second is intended to reactivate RB1 tumor suppressor function, principally through the use of CDK4/6 inhibitors that have shown promise in clinical trials." (PMID 26160835, 2015). "For instance, oncolytic viruses carrying deletions in the E1A viral protein, which render viral replication dependent on RB1 inactivation, were developed to selectively kill RB1-defective tumor cells." (PMID 26160835, 2015). "We demonstrate that TALEN-mediated targeting of rb1 results in highly penetrant tumor formation in genetic mosaic adults." (PMID 26345384, 2015). "Inactivation of the retinoblastoma (RB1) tumor suppressor is one of the most frequent and early recognized molecular hallmarks of cancer." (PMID 26160835, 2015). "The relative expression of the genes CDKN2A, CDKN2B, and RB1 was significantly decreased in all the examined tumor grades." (PMID 26317630, 2015). "At the same time, highly heterogeneous short structural variants were discovered in PTEN, RB1, and BRCA2 in all tumor and CTC samples." (PMID 26575023, 2015). "Rb1 and P16 show inverse expression pattern according to tumor grade with more frequent Rb1 in low grade vs. more frequent P16 in grade three tumors." (PMID 26043844, 2015). "In tumours with functional RB1, inhibition of CDK4 and CDK6 activity has a significant suppressive effect on cell proliferation." (PMID 25896606, 2015). "Conversely, the expression of RB1 was undetectable in the NEPC tumor lines LTL352 and LTL370 while LTL331R exhibited a modest increase." (PMID 25859291, 2015). "We then aggregated all the obtained P values from the genes connected to RB1 across tumour types, and computed the FDRs37." (PMID 26436532, 2015). "In addition, loss of the well-known tumour suppressor RB1 was found to occur at a higher frequency in tumours that had developed characteristics such as solid growth, moderate to severe nuclear pleomorphism, high mitotic index and invasive growth into tumour stroma." (PMID 25955013, 2015). "Mutant allele analysis is consistent with tumor initiation due to somatic inactivation of rb1, revealing a conserved role for rb1 in tumor suppression across vertebrates." (PMID 26345384, 2015).